SPDL1 (spindle apparatus coiled-coil protein 1)
Diseases named in the same sentence as SPDL1 in open-access papers (continued):
Sharing a sentence is not in itself a finding about the gene and the disease.
cancer (continued). "The function of spindle apparatus coiled-coil protein 1 (SPDL1) as a cancer-promoting gene has been reported in a number of studies." (PMID 35093072, 2022). "In several cancers, SPDL1 expression was found to be significantly correlated with the pathological stages by the “Pathological Stage Plot” module of GEPIA2 in ACC, KICH, KIRP, LIHC, LUAD, SKCM (P < .05), but not in others." (PMID 35093072, 2022). "It is simultaneously clear that due to very little available information regarding SPDL1 in human cancers, many aspects of its function and regulation are still unresolved." (PMID 35163739, 2022). "It is also uncommon to find overexpression of tumor suppressor in cancer tissue, yet SPDL1 expression as continuous and categorical variable was significantly elevated in CRC tissues compared to the control both at the protein and mRNA levels." (PMID 35163739, 2022). "Furthermore, it was found that PRR11 regulates PDL1 via SPDL1, impacting immunotherapeutic efficacy in both cancers." (PMID 38760964, 2024). "Finally, the correlation between the SPDL1 expression and cancer immune infiltrating cells was evaluated by analyzing data from the TCGA database." (PMID 39196978, 2024). "In recent years, several studies have showed that SPDL1 participates in numerous types of cancer in humans, and could be used as a prognostic marker." (PMID 39148981, 2024). "Further, inhibiting the SPDL1 expression could effectively slow down cancer cell growth and migration." (PMID 39196978, 2024). "As well, previous molecular signatures and therapies from different types of cancer could affect sPDL‐1 release." (PMID 37799808, 2023). "The TIMER2.0 was used to analyze the expression of SPDL1 in all cancer types." (PMID 35093072, 2022). "SPDL1 has been found to play a role in cancer progression; however, its role in ESCA remains unknown." (PMID 35664322, 2022). "Therefore, we analyzed the SPDL1 methylation levels in cancer tissues and normal tissues using the UALCAN." (PMID 35093072, 2022). "According to several studies that have reported the role of soluble checkpoint molecules in the promotion and progression of cancer, downregulating immune activation, here we demonstrated that IFNγ, sPDL1 and sCTLA4 play important roles in regulating the response to TKI treatment." (PMID 32937860, 2020). "In addition, the SPDL1 co-expressed genes are related to cancer progression." (PMID 39196978, 2024). "Inhibiting SPDL1 expression could effectively slow down cancer cell growth and migration." (PMID 39196978, 2024). "Moreover, high expression of sPDL-1 in the peripheral blood of cancer patients could represent a mechanism of resistance that is correlated to the failure of immunotherapy treatment." (PMID 36430974, 2022). "Therefore, SPDL1 may be of high value in cancer progression." (PMID 35664322, 2022). "In 5 cancer types, including ACC, CESC, COAD, READ, and SARC, SPDL1 expression was positively correlated with the aneuploidy." (PMID 35093072, 2022). "Among them, SPDL1 expression level was increased in 44 ESCA tissues and significantly decreased in 9 cancer patients." (PMID 35664322, 2022). "A large proportion of cancer patients benefit from immune checkpoint therapy, while few studies focused on the relationship between soluble PD1 (sPD1) and soluble PDL1 (sPDL1) in serum and immune status of patients." (PMID 36479137, 2022). "Thus, in this study we have analyzed the molecular features of SPDL1, such as gene expression, genetic alteration, protein expression, methylation level, protein phosphorylation, immune infiltration, survival prognosis, and gene enrichment analysis in different cancer types." (PMID 35093072, 2022).
cancer (continued). "Our results also indicated that SPDL1 expression was significantly correlated with HRD, LOH, number of neoantigens, the aneuploidy in 21, 15, 5 and 9 cancer types respectively." (PMID 35093072, 2022). "Cancer stages III and IV were analyzed together due to a limited size of the patients in stage IV; this was also why we failed to analyze OS stratified according to the expression of SPDL1 and the metastatic status of TCGA patients at diagnosis." (PMID 35163739, 2022). "As far as we know, there is no information available about the analysis of SPDL1 in pan-cancers." (PMID 35093072, 2022). "Unfortunately, sPDL1 could only distinguish new-onset cancer-related DM from DM without malignancies with a relatively poor sensitivity of 68%." (PMID 30766892, 2019). "Interestingly, the serum level of sPDL1 was higher in new-onset cancer-related DM compared to DM without malignancies or stable cancers with DM." (PMID 30766892, 2019).
SPDL1 also shares sentences with these, for which no sentence is quoted: renal cell carcinoma (29 papers); non-small cell lung carcinoma (26); hepatocellular carcinoma (23); pancreatic cancer (19); diffuse large B-cell lymphoma (15); glioma (11); lymphoma (11); multiple myeloma (10); bladder cancer (9); infection (9); autoimmune disease (7); soft tissue sarcoma (7); metastatic disease (6); rectal cancer (6); adenocarcinoma (5); brain tumors (5); endometriosis (5); mesothelioma (5); Pleural effusion (5); squamous cell carcinoma (5); triple-negative breast carcinoma (5); viral infections (5); acute pancreatitis (4); B-cell lymphoma (4); benign tumors (4); coronary artery disease (4); glioblastoma (4); Infertility (4); pneumonia (4); preeclampsia (4).
A further 110 diseases each share a sentence with SPDL1 in 4 papers or fewer.